NOS1 (nitric oxide synthase 1)
Diseases named in the same sentence as NOS1 in open-access papers (continued):
Sharing a sentence is not in itself a finding about the gene and the disease.
ovarian carcinoma (12 papers, 2008 to 2024). A malignant neoplasm originating from the surface ovarian epithelium. "On the other hand, NOS1 inhibition with NG-nitro-L-arginine methyl ester in ovarian cancer cell lines coincided with diminished cell proliferation, migration and invasion." (PMID 38397798, 2024). "Our previous study showed that NOS1 expression in ovarian cancer promoted tumor glycolysis and growth through S-nitrasylation of the key enzyme (PFK1)." (PMID 35538490, 2022). "Our study showed that NOS1 bound with the key enzyme of glycolysis and modulated metabolic rewiring in ovary cancer progression." (PMID 35538490, 2022). "We constructed an ovarian cancer cell line (SKOV3) that stably deleted NOS1 using CRISPR/Cas9 technology." (PMID 33859186, 2021). "Here, we explored the role of PFKM S-nitrosylation modification induced by NOS1 on the metabolic switch in ovarian cancer." (PMID 33859186, 2021). "Analysis of NOS1 expression in human ovarian cancer tissues from the GSE database (GSE14407) found that NOS1 expression in cancer tissues was higher than in normal tissues." (PMID 33859186, 2021). "For example, ASCL3 is overexpressed in breast cancer, and NOS1, in ovarian cancer cell lines." (PMID 35774364, 2022). "For instance, higher NOS1 expression promotes the proliferation and invasion of ovarian cancer." (PMID 35807116, 2022). "These included LAMA3 mutations (lung squamous) and NOS1 mutations (breast cancer), which were identified as MEK inhibitor-specific biomarkers, and ST18 mutations (lung adenocarcinoma and ovarian cancer), which were identified as HDAC inhibitor-specific biomarkers." (PMID 28561042, 2017). "Therefore, to test whether NOS1 affected the kinetic correlation constant of PFKM in ovarian cancer cells, we measured the enzyme activity of PFKM at gradient substrate concentrations." (PMID 33859186, 2021). "Nitric oxide synthase 1 (NOS1) modulates S-nitrosylation at Cys351 of PFKM, which contributes to the reprogramming of glucose metabolism in ovarian cancer cells." (PMID 36311734, 2022). "The expressions of both NOS1 and PFKM increase in different kinds of tumors and positively correlated with the progressive stages of ovarian cancer." (PMID 33859186, 2021). "Here we demonstrated that NOS1 induces PFKM S-nitrosation at Cys351 to stabilize tetramer of PFK1 and increase its activity, leading to the increase of the glycolysis in ovarian cancer cells." (PMID 33859186, 2021). "NOS1 and NOS3 mRNA levels were detected in A2780 and 2008 cells, but were almost undetectable in ES2 cells and other ovarian cancer cell lines that we tested." (PMID 25924901, 2015).
Achalasia (11 papers, 2015 to 2025). A disorder of esophageal motility characterized by the inability of the lower esophageal sphincter to relax during swallowing and by inadequate or lacking peristalsis in the lower half of the body of the esophagus. "The two consanguineous siblings (individuals 11 and 12) share, besides the homozygous VUS in SETD1B, also homozygous VUS in NBAS (associated with immune defects) and NOS1 (associated with achalasia)." (PMID 34345025, 2021). "Additionally, an exome analysis of two siblings with infant-onset achalasia revealed homozygosity for a premature stop codon in the gene encoding NOS1 (at residue Tyr1202, instead of at residue 1435)." (PMID 30092016, 2018). "Recent studies have also shown multiple genetic mutations such as nitric oxide synthase 1 gene (NOS1), VIP receptor 1, IL23R, IL10 promoter, IL33, and protein tyrosine phosphatase non-receptor 22 (PTPN22) to be associated with the development of achalasia." (PMID 26198208, 2015). "On the other hand, in the digestive tract, the production of NO by the neuronal NOS (nNOS, encoded by NOS1 gene) explains that the patients mutated in NOS3 do not suffer from achalasia." (PMID 36941667, 2023).
dystrophin deficiency (11 papers, 2006 to 2021). "NOS1 is a member of the DGC and is lost in a situation of dystrophin deficiency." (PMID 31817415, 2019).
cardiac hypertrophy (10 papers, 2010 to 2022). "In this study, using mice with a cardiac-specific deficiency in Prdm16, we confirmed the development of cardiac hypertrophy and noted decreases in BP in Prdm16CKO mice, which we attributed to the upregulation of NOS1." (PMID 35862303, 2022). "Further, our findings suggest that NOS1 is important in reducing BP in mice that present with cardiac hypertrophy due to a cardiac-specific deficiency in Prdm16." (PMID 35862303, 2022). "In combination with the recovery results above, we suggest that NOS1 is chiefly responsible for hypotension in Prdm16CKO mice that present with cardiac hypertrophy." (PMID 35862303, 2022). "Indeed Nos3 KO mice just like triple Nos1, Nos2, Nos3 KO mice develop cardiac hypertrophy." (PMID 35874523, 2022). "Early cardiac hypertrophy induced by angiotensin II did not change either NOS1 or NOS2 mRNA expressions (not illustrated), NOS3 mRNA expression or NOS3 protein expression." (PMID 21151982, 2010). "NOS1 and NOS2 may also slightly prevent cardiac hypertrophy since hypertrophy is significantly higher in triple KO mice in comparison to Nos3 KO mice, however, Nos1 or Nos2 KO mice do not develop cardiac hypertrophy." (PMID 35874523, 2022).
cognitive decline (10 papers, 2015 to 2024). "Another significant finding is that the circuit of miR‐328‐5p/Nos1 may participated in POD‐like behavior induced long‐term cognitive decline, while it has to be noted that only Nos1 but not miR‐328‐5p is significantly correlated with Hip related FC." (PMID 39317458, 2024).
erectile dysfunction (10 papers, 2005 to 2025). Persistent or recurrent inability to achieve or to maintain an erection during sexual activity. "Thus, it is possible that genetic markers on NOS1 and PDE5A may help to explain the natural vulnerability to the onset of NO pathway imbalances that culminate in a greater risk of developing erectile dysfunction and having more severe degrees of this disease." (PMID 37240727, 2023).
breast carcinoma (9 papers, 2017 to 2024). "Except for CCL19, RAET1G, IL12B, CXCL13, CCL22, and NOS1 were significantly highly expressed in breast cancer at the mRNA level." (PMID 36292723, 2022). "Tryptanthrin effectively inhibited tumor growth in 4 T1 murine breast cancer model; modulated expression levels of nitric oxide synthase 1 (NOS1), COX-2, and nuclear factor kappa-B (NF-κB) in mouse tumor tissues; and regulated some factors such as IL-2, IL-10, and TNF-α in mice." (PMID 37789475, 2021).
ischemic heart disease (9 papers, 2016 to 2025). "It was thereby confirmed that NOS1 is the most important risk gene for NOS-dependent coronary artery disease." (PMID 33374571, 2020). "Moreover, NOS1 has been shown to play a role in endothelial function and has been associated with coronary artery disease." (PMID 41452882, 2025). "Moreover, genes enriched in this pathway were related to an increased risk of coronary heart disease, such as NRG1, EGR2, and NOS1." (PMID 36032780, 2022). "Our findings indicate that NOS1 may be significant in the pathophysiology of human ischemic heart disease with a preservative role in maintaining myocardial homeostasis." (PMID 27041589, 2016).
Hypercholesterolemia (8 papers, 2011 to 2025). An increased concentration of cholesterol in the blood. "The convergence of mitochondrial redox regulation (via SIRT3–SOD2) and hypercholesterolemia-induced hypoxia signaling on NOS1 highlights its centrality in CRC pathophysiology." (PMID 41268067, 2025). "Collectively, the pharmaceutical blockade of NOS1 through its specific inhibitor Nω-Propyl-L-arginine is a promising therapeutic strategy for hypercholesterolemia-related CRC." (PMID 38755702, 2024). "In this study, our results showed that although all three NOSs exist and contribute to total NO production in CRC cells, only NOS1 was shown to be the main mediator of hypercholesterolemia-induced CRC." (PMID 38755702, 2024). "More importantly, our results suggested that selective inhibition of NOS1 with its specific inhibitor Nω-Propyl-L-arginine is a suitable therapeutic strategy for hypercholesterolemia-related CRC with both efficacy and toxicity reduction." (PMID 38755702, 2024). "This induction of hypoxia signaling transcriptionally upregulates NOSs, especially NOS1, which is critical to hypercholesterolemia-induced CRC growth and survival." (PMID 38755702, 2024). "Our findings further confirmed that the selective blockade of NOS1 is sufficient for inhibiting tumor progression in hypercholesterolemia-related CRC." (PMID 38755702, 2024). "To this end, we employed the highly selective NOS1 inhibitor Nω-Propyl-L-arginine to determine its potential therapeutic effect on hypercholesterolemia-related CRC." (PMID 38755702, 2024). "We compared the effects of hypercholesterolemia on tissue culture, a mouse xenograft model, and a chemical carcinogenesis mouse model, and identified NOS1 as an unidentified direct target of HIF-1α that contributes to the oncogenic role of hypercholesterolemia in CRC." (PMID 38755702, 2024). "Of note, our study found that NOS1 is the most significantly up-regulated NOS in hypercholesterolemia-related CRC models, which means that NOS1 may act as an important regulator in the development of hypercholesterolemia-related CRC." (PMID 38755702, 2024). "Therefore, we postulate that the selective inhibition of NOS1 may be a suitable therapeutic strategy for hypercholesterolemia-related CRC with both efficacy and toxicity reduction." (PMID 38755702, 2024). "Thus, protein S-nitrosylation by NOS1 may be critical for hypercholesterolemia-induced tumor promotion in CRC." (PMID 38755702, 2024).
Arrhythmia (7 papers, 2016 to 2025). Any cardiac rhythm other than the normal sinus rhythm. "The studies showed that the inhibition of NOS1 decreased RYR2 activity because of reducing Ca2+ sparks and shortened action potential causing arrhythmia susceptibility." (PMID 35924220, 2022). "The present studies have shown that the inhibition of NOS1 decreased RYR2 activity because of reducing Ca2+ sparks and shortened action potential causing arrhythmia susceptibility." (PMID 35924220, 2022). "Furthermore, the inhibition of NOS1 in the SR decreased RYR2 activity because of reducing Ca2+ sparks and shortened action potential causing arrhythmia susceptibility." (PMID 35924220, 2022).
cardiomyopathy (7 papers, 2009 to 2020). A disease of the heart muscle or myocardium proper. "The use of transgenic NOS1 over-expression in mdx mice prevents the development of many signs of cardiomyopathy." (PMID 31817415, 2019).
Hypoglycemia (7 papers, 2014 to 2024). A decreased concentration of glucose in the blood. "VMNvl GABA neurons exhibited amplified NOS1 transcript profiles in response to hypoglycemia, a stimulatory response that was blunted by GLUT2 gene knockdown." (PMID 38902332, 2024). "The direction of GLUT2 regulation of NOS1 and Ghrh gene expression is glucose-dependent, as control is inhibitory during euglycemia, yet stimulatory during hypoglycemia." (PMID 38902332, 2024).
autism (6 papers, 2017 to 2025). Persistent deficits in social interaction and communication and interaction as well as a markedly restricted repertoire of activity and interest as well as repetitive patterns of behavior. "JD and KF both wrote the review, JD conducted the original research on autism and NOS1 as cited, KF conceived and designed experiments for the NOS1 experiments as cited." (PMID 27870449, 2017).
COVID-19 (6 papers, 2021 to 2025). A disease caused by infection with severe acute respiratory syndrome coronavirus 2. "There is currently no direct evidence linking specific polymorphisms in the inducible nitric oxide synthase (iNOS or NOS2) and NOS1 genes to the severity of COVID-19." (PMID 41209585, 2025). "In our study group, we determined that serum nitrate–nitrite levels, the metabolites of NO, and NOS1 levels were higher in all COVID-19 cases compared with controls." (PMID 34836309, 2021).
infertile (6 papers, 2009 to 2025). "Humans and mice with loss-of-function mutations in nNOS (encoded by NOS1 and Nos1 genes, respectively) are infertile and global inhibition or deletion of NO production precludes leptin-induced LH secretion." (PMID 40276575, 2025). "Loss-of-function mutation in NOS1/Nos1 gene in humans and mice cause infertility and blockade of nitric oxide neurotransmission disrupts leptin actin in reproductive axis." (PMID 39007235, 2024). "Knock-out mouse for NOS1 gene encoding for the nNOS resulted in hypogonadotropic hypogonadism, infertility and dose-dependent defects in olfaction, hearing, and cognition." (PMID 36619551, 2022). "In infertile men, only weak positive correlations were observed, specifically between PGE2 and 6-keto-PGF1α, and between NOS1 and SOD1." (PMID 41462670, 2025). "In the infertile group, PGE2/6-keto-PGF1α negatively correlated with progressive motility, PGE2 positively with 6-keto-PGF1α, and NOS1 positively with SOD1." (PMID 41462670, 2025).
mental disorder (6 papers, 2017 to 2026). A disease that has its basis in the disruption of mental process. "No apparent evidence from the literature seems to implicate FBXO21 with mental disorders, and the observed association is probably due to the strong linkage disequilibrium with the NOS1 variant (r2=0.897)." (PMID 28195573, 2017). "In our review, we have summarized information regarding all NOS1, NOS2, NOS3, and NOS1AP single nucleotide variants (SNVs) involved in the development of mental disorders and neurological diseases/conditions." (PMID 32111088, 2020). "In our review, we have decided to summarize information regarding all NOS1, NOS2, NOS3, and NOS1AP SNVs involved in the development of mental disorders and neurological diseases/conditions." (PMID 32111088, 2020).
Ventricular arrhythmia (6 papers, 2016 to 2025). "It has been also shown that NOS1 inhibition leads to the development of ventricular arrhythmias under condition of elevated cytosolic [Ca]." (PMID 30574097, 2018). "Under condition of NOS1 inhibition, the XO inhibitor allopurinol or the NO● donor GSNO could prevent ventricular arrhythmias." (PMID 30574097, 2018).
Dyskinesia (5 papers, 2019 to 2026). A movement disorder which consists of effects including diminished voluntary movements and the presence of involuntary movements. "The last three along with COMT rs165815, and NOS1 rs2293054 were associated with time to occurrence of dyskinesia within the clinical-pharmacogenetic model." (PMID 31156712, 2019). "NOS1 rs2293054 influences splicing according to the SNP function prediction tool, which might decrease protein production and thus protect against dyskinesia." (PMID 31156712, 2019).
atrial fibrillation (4 papers, 2018 to 2024). A disorder characterized by an electrocardiographic finding of a supraventricular arrhythmia characterized by the replacement of consistent P waves by rapid oscillations or fibrillatory waves that vary in size, shape and timing and are accompanied by an irregular ventricular response. "A reduction in both dystrophin and neuronal nitric oxide synthase (NOS1) secondary to microRNA-31 (miR-31) up-regulation contributes to the atrial electrical remodelling that underpins human and experimental atrial fibrillation (AF)." (PMID 38270932, 2024).
cerebral infarction (4 papers, 2013 to 2022). An ischemic condition of the brain, producing a persistent focal neurological deficit in the area of distribution of the cerebral arteries. "In the cerebral infarction model, NOS1-deficient mice had smaller infarct ratio and milder neurological dysfunction when compared with controls, suggesting that NOS1 is detrimental for cerebral infarction." (PMID 24082858, 2013).
colon cancer (4 papers, 2020 to 2025). "Different NOS3 and NOS1 polymorphisms described in colorectal tissue are suspiciously associated with the development of colon cancer." (PMID 40642105, 2025). "Previous studies have demonstrated that NOS1 promotes the survival of nasopharyngeal carcinoma cells and cancer-associated fibroblasts, but little has been related to colon cancer." (PMID 32668616, 2020). "According to the study, individuals who expressed more NOS1 tended to have shorter overall survival times than those who expressed less NOS1 among all colon cancer patients." (PMID 40642105, 2025). "On the other hand, knockdown of SIRT3 reversed NOS1-induced apoptosis resistance of SW480 and SW620 colon cancer cells." (PMID 34360883, 2021). "For instance, mitochondrial neuronal nitric oxide synthase (nNOS, NOS1) could increase SIRT3 activity and thereby activating SOD2 to regulate ROS production properly, thus, suppressing apoptosis of colon cancer cells." (PMID 35832551, 2022).
colorectal cancer (4 papers, 2021 to 2026). A primary or metastatic malignant neoplasm that affects the colon or rectum. "Mechanically, the oxLDL promotes the oxidant stress-dependent induction of hypoxia signaling to transcriptionally up-regulate NO synthase (NOS) especially NOS1 expression in colorectal cancer (CRC) cells." (PMID 38755702, 2024).
dementia (4 papers, 2013 to 2023). Loss of intellectual abilities interfering with an individual's social and occupational functions. "The presence of the NOS1 rs2293054 G allele only in patients with dementia or AD, in our study, was a surprising outcome." (PMID 36829875, 2023). "On the other hand, all carriers of two NOS1 rs2293054 G alleles had dementia (p = 0.019)." (PMID 36829875, 2023). "Among antioxidative genes, CAT, GSTP1, NOS1, NFE2L2, and KEAP1 were associated with dementia or AD." (PMID 36829875, 2023).
glioblastoma (4 papers, 2020 to 2024). The most malignant astrocytic tumor (WHO grade IV). "Univariate analyses also demonstrated that SLC7A7 and ASS1 were hazardous prognostic factors for glioblastoma, while DDAH1 and NOS1 were proved as protective factors for glioblastoma." (PMID 37214463, 2023).
Headache (4 papers, 2010 to 2022). Cephalgia, or pain sensed in various parts of the head, not confined to the area of distribution of any nerve. "In parallel with Turkish studies, a noteworthy study of genes NOS1 and NOS3 SNVs as risk factors for the development of medication overuse headaches (in patients with M) was carried out in the Japanese population." (PMID 34200123, 2021). "Over the past 15 years, works aimed at finding associations of NOS1, NOS2, and NOS3 genes with the development and course of headaches (H) have been carried out using the example of patients with M." (PMID 34200123, 2021). "In the study on the carriage of rs3782218 in the NOS1 gene, the data obtained were found to be consistent with the HWE law in group 1 (TTH and AH overlap syndrome)—χ2 = 0.016; p-value = 0.99, group 2 (AH without headache)—χ2 = 0.248; p-value = 0.88 and group 3 (control)—χ2 = 0.008; p-value = 0.1." (PMID 36292708, 2022).
multiple sclerosis (4 papers, 2013 to 2023). A progressive autoimmune disorder affecting the central nervous system resulting in demyelination. "Additionally, Timp2 and Nos1 are assumed to be involved in the pathogenesis of multiple sclerosis." (PMID 36817487, 2023). "The association study of NO-encoding genes with multiple sclerosis (MS) demonstrated no statistically significant results in relation to the NOS1 gene, unlike other enzymes of this family (see Section 2.3.7 and Section 2.4.10 on “Multiple Sclerosis” regardingNOS2 and NOS3)." (PMID 32111088, 2020).